SMR3B (submaxillary gland androgen regulated protein 3B)
Synonyms: PBII; PRL3; PROL3; P-B; SMR1B
Tractability: Antibody: UniProt places it where antibodies can reach, with medium confidence; UniProt predicts a signal peptide or a membrane-spanning region; its Gene Ontology location is reachable by antibodies, with medium confidence.
Gene: Protein-coding gene on chromosome 4 (70,370,093 to 70,390,244, forward strand). Ensembl gene ENSG00000171201.
Subcellular location: Secreted
Gene Ontology:
Molecular function: protein binding; endopeptidase inhibitor activity
Biological process: regulation of sensory perception of pain
Cellular component: extracellular exosome; extracellular region
Genetic constraint (gnomAD): Loss-of-function variants: 0 observed, 2.66 expected, observed/expected ratio (o/e) 0, 90% interval 0 to 1.09. That is too few expected variants to judge how well the gene tolerates losing a copy. Missense variants: 114 observed, 103 expected, observed/expected ratio (o/e) 1.11, 90% interval 0.95 to 1.29. Synonymous variants: 42 observed, 34.99 expected, observed/expected ratio (o/e) 1.2, 90% interval 0.94 to 1.55.
Homologues: Orthologues: chimpanzee SMR3B (96% identical).
Diseases named in the same sentence as SMR3B in open-access papers:
SMR3B is named in the same sentence as 9 diseases in open-access papers, as found by Europe PMC text mining. Sharing a sentence is not in itself a finding about the gene and the disease. The quoted sentences say what the papers report.
breast carcinoma (1 paper, 2026). "In conclusion, our experimental results collectively establish SMR3B as a prognostic biomarker in both breast cancer and thyroid cancer, significantly restraining key oncogenic phenotypes including proliferation, migration, and invasion of cancer cells." (PMID 41601694, 2026).
dry eye (1 paper, 2025). "CST4 and SMR3B are considered as potential dry eye biomarkers." (PMID 40700273, 2025).
hepatocellular carcinoma (1 paper, 2019). A malignant tumor that arises from hepatocytes. "Additionally, we are not aware of any specific study on SMR3B in tumours, but SMR3B amplification has been detected in osteopontin (OPN)-positive hepatocellular carcinoma." (PMID 31297036, 2019).
salivary gland tumors (1 paper, 2026). "The consistent absence of SMR3B—a salivary gland-specific protein—and its associated peptides in both tumor tissue extracts and patient saliva samples highlights its potential as a hallmark feature of salivary gland tumors, suggesting tumor-induced suppression of gland-specific protein expression." (PMID 41601694, 2026).
thyroid cancer (1 paper, 2026). "Despite limited studies in thyroid cancer, SMR3B’s endocrine/immune-metabolic roles suggest biomarker potential, warranting further exploration." (PMID 41601694, 2026).
tumor (5 papers, 2019 to 2026). "We identified key functional gene modules linked to tumor stemness and therapy resistance, while machine learning prioritized SMR3B as a prognostic biomarker attenuating proliferation, invasion, and metastasis." (PMID 41601694, 2026). "As GATA3 protein has a role in expression regulation, lower level of SMR3B expression in tumor carrying GATA3 mutations can be explained by this fact." (PMID 33462316, 2021). "no peptides derived from four saliva-specific proteins (SATH, SMR3B, HTN1, HTN3) were identified in extracts from tumor tissue." (PMID 39201484, 2024). "Extracts derived from tumor tissue do not contain peptides derived from statherin (STATH) and three other proteins: submaxillary gland androgen-regulated protein 3b (SMR3B), histatin 1 (HTN1), and histatin 3 (HTN3)." (PMID 39201484, 2024). "The surprising result was that extracts from tumor tissue did not contain peptides derived from salivary gland-specific proteins (STATH, SMR3B, HTN1, HTN3)." (PMID 39201484, 2024). "The lack of identification of peptides from proteins STATH, SMR3B, HTN1, and HTN3 in extracts from tumor tissues may suggest that there is a complete suppression of the production of these proteins in tumor tissues." (PMID 39201484, 2024). "However, regardless of the tumor type, the effect is the same: a lack of occurrence of peptides derived from proteins STATH, SMR3B, HTN1, and HTN3." (PMID 39201484, 2024). "Moreover, SMR3B gene (submaxillary gland androgen-regulated protein 3B) was identified to have differential expression between GATA3 mutant and non-mutant tumor tissues as mutant samples indicate a lower level of expression." (PMID 33462316, 2021).
SMR3B also shares sentences with these, for which no sentence is quoted: triple-negative breast carcinoma (2 papers); cancer (1); periodontal diseases (1).